BEAN1 (brain expressed associated with NEDD4 1)
Synonyms: BEAN; SCA31
Tractability: Antibody: UniProt predicts a signal peptide or a membrane-spanning region.
Gene: Protein-coding gene on chromosome 16 (66,427,295 to 66,493,529, forward strand). Ensembl gene ENSG00000166546.
Subcellular location: Membrane
Subcellular location (Human Protein Atlas): Nucleoplasm; Centrosome
Gene Ontology:
Cellular component: membrane
Genetic constraint (gnomAD): Loss-of-function variants: 17 observed, 17.57 expected, observed/expected ratio (o/e) 0.97, 90% interval 0.66 to 1.45. The upper end of that interval is the gene's LOEUF score, 1.45, which puts it in group 5 of 6, group 1 being the genes least tolerant of losing a copy. Missense variants: 359 observed, 362.97 expected, observed/expected ratio (o/e) 0.99, 90% interval 0.91 to 1.08. Synonymous variants: 142 observed, 144.75 expected, observed/expected ratio (o/e) 0.98, 90% interval 0.86 to 1.13.
Homologues: Orthologues: chimpanzee BEAN1 (98% identical), macaque BEAN1 (95% identical), pig BEAN1 (86% identical), guinea pig BEAN1 (84% identical), dog BEAN1 (83% identical), mouse Bean1 (80% identical), rat Bean1 (79% identical).
Diseases named in the same sentence as BEAN1 in open-access papers:
BEAN1 is named in the same sentence as 10 diseases in open-access papers, as found by Europe PMC text mining. Sharing a sentence is not in itself a finding about the gene and the disease. The quoted sentences say what the papers report.
spinocerebellar ataxia type 31 (5 papers, 2020 to 2025). "Spinocerebellar ataxia type 31 (SCA31) is caused by non-coding pentanucleotide repeat expansions in the BEAN1 gene." (PMID 33785066, 2021). "Spinocerebellar ataxia type 31 (SCA31) is a neurological disease caused by insertion of a 2.5 to 3.8 kb repeat that includes the long TGGAA stretch present in a common intronic region of BEAN1 (brain expressed associated with NEDD4-1) and thymidine kinase 2 (TK2) genes." (PMID 32093161, 2020). "Repeats of pentapeptide microsatellites in the shared exon of brain expressed associated with NEDD4 1 (BEAN1) and thymidylate kinase 2 (TK2) are responsible for spinocerebellar ataxia type 31 (SCA31)." (PMID 32951567, 2021).
Ataxia (2 papers, 2019 to 2021). Ataxia refers to impaired coordination of voluntary muscle movement. "We also analyzed the co-expression network of those ataxia risk genes and revealed a central role of Eef2, Grid2, Tubb4a in the co-expression networks, while Ttbk2 and Bean1 have few interactions with other ataxia risk genes." (PMID 30690467, 2019). "We find that splicing aberrations disrupt the expression of many key cerebellar PC genes, many of which (e.g., Itpr1, Grid2, Ca8, Bean1, etc.)can individually compromise cerebellar function and lead to ataxia." (PMID 34910524, 2021).
Parkinsonism (1 paper, 2025). Characteristic neurologic anomaly resulting from degeneration of dopamine-generating cells in the substantia nigra, a region of the midbrain, characterized clinically by shaking, rigidity, slowness of movement and difficulty with walking and gait. "Several patients with ataxic BEAN1/TK2 repeat expansions also presented with parkinsonism; however, they did not fulfill the criteria for a diagnosis of PD." (PMID 40765612, 2025).
BEAN1 also shares sentences with these, for which no sentence is quoted: amyotrophic lateral sclerosis (1 paper); cancer (1); essential tremor (1); hereditary cerebellar ataxia (1); neurological disease (1); neuronal intranuclear inclusion disease (1); spinocerebellar ataxia type 36 (1).